DPP4 (dipeptidyl peptidase 4)
Diseases named in the same sentence as DPP4 in open-access papers (continued):
Sharing a sentence is not in itself a finding about the gene and the disease.
metabolic syndrome (continued). "Dyslipidemia and liver steatosis are unaffected by the genetic elimination of Dpp4 in aged, HFHC-fed mice." (PMID 36472923, 2023). "Several investigations report increased circulating DPP4 concentration in obese individuals, mostly in the presence of metabolic syndrome." (PMID 36140405, 2022). "The serum DPP-4 levels were positively correlated with adipocyte size and metabolic-syndrome indices, such as BMI, insulin, and leptin, and negatively correlated with age and adiponectin levels." (PMID 35893426, 2022). "In our previous reports, we demonstrated the existence of an association between higher sDPP4/DPP4 activity and the diagnosis of T2DM and metabolic syndrome." (PMID 36140405, 2022). "A different research group found that physical exercise decreased DPP4 activity in patients with metabolic syndrome." (PMID 36204396, 2022). "In multiple logistic regression, the increase of DPP4 gene expression before HCST (as well as its change between pre- and post-HSCT status) was associated with dyslipidemia." (PMID 34298827, 2021). "A human metabolic syndrome study found that women had decreased plasma Dpp4 activity levels in the metabolic syndrome patients compared to control patients." (PMID 34710177, 2021). "Previous studies have shown the participation of DPP4 in the pathogenesis of hyperglycemia, IR, dyslipidemia, oxidative stress, inflammation, fatty liver (FL) and SA." (PMID 34178021, 2021). "Accumulating clinical evidence has demonstrated that plasma DPP4 activity is significantly increased in human subjects with polycystic ovary syndrome and metabolic syndrome." (PMID 33312197, 2020). "The objective of this study was to analyze the differences between plasma GLP-1 and DPP4 activity in male and female patients with metabolic syndrome, and its relationship with physiological and metabolic parameters." (PMID 29958403, 2018). "Patients treated with DPP-4 inhibitors showed significantly higher systolic blood pressure (BP), diastolic BP, serum albumin, dyslipidemia, and eGFR reduction rate (baseline to 12 months) than the untreated patients did." (PMID 29187821, 2017). "DPP-4 inhibitors (HR, 0.761; 95% CI, 0.633–0.914; P = 0.004), dyslipidemia (HR, 0.718; 95% CI, 0.576–0.895; P = 0.003), and ACEI/ARBs (HR, 0.681; 95% CI, 0.511–0.908; P = 0.009) significantly reduced the risk of eGFR decline >20%." (PMID 29187821, 2017). "Patients treated with DPP-4 inhibitors showed significantly higher systolic BP, diastolic BP, serum albumin, serum sodium, dyslipidemia, and eGFR reduction rate (baseline to 3 and 12 months) than the DPP-4 inhibitor-untreated patients did." (PMID 29187821, 2017). "Clinical evidence indicates that the ability of DPP4 inhibitors to ameliorate plasma dyslipidemia is likely to contribute to the cardiovascular benefits." (PMID 27654253, 2016). "Genetic or pharmacological intervention targeted toward DPP4 activity improved plasma dyslipidemia in mice." (PMID 27654253, 2016). "Circulating DPP-4 concentrations were increased in obese subjects and correlated with parameters of the metabolic syndrome, such as body mass index, waist circumference, and plasma fasting insulin concentration." (PMID 27652270, 2016). "Recently, DPP4 was identified as a new adipokine, possibly linking AT to IR and the metabolic syndrome." (PMID 26146634, 2015). "Clinical studies in T2DM with DPP-4 inhibitors provide evidences that incretin-based therapies improve fasting and postprandial glycemia and somewhat also dyslipidemia." (PMID 26170902, 2015). "In multivariable-adjusted models, the odds ratio (OR) for incident metabolic syndrome comparing the highest with the lowest quartiles of DPP4 activity and active GLP-1 were 2.82, 0.45 for men and 2.48, 0.36 for women respectively." (PMID 24647445, 2014). "A similar association was observed between DPP4 activity, active GLP-1 and each component of the metabolic syndrome except for high diastolic blood pressure and microalbuminuria (all P<0.05)." (PMID 24647445, 2014).
metabolic syndrome (continued). "In this prospective study, we demonstrate, for the first time, that plasma DPP4 activity predict the onset of IR and metabolic syndrome." (PMID 24647445, 2014). "In multivariable -adjusted models [model 5], the OR for developing metabolic syndrome comparing subjects in the highest with those in the lowest quintile of baseline DPP4 activity and active GLP-1 were 2.82, 0.45 for men and 2.48, 0.36 for women respectively." (PMID 24647445, 2014). "We performed ROC curve analyses to evaluate the additional predictive ability of DPP4 activity beyond the information provided by the components of the metabolic syndrome at baseline." (PMID 24647445, 2014). "The dipeptidyl peptidase-4 (DPP4) enzyme is a novel adipokine potentially involved in the development of the metabolic syndrome (MetS)." (PMID 23379505, 2013). "In addition, the DPP4 inhibitors vildagliptin and sitagliptin suppressed postprandial elevation of triglycerides and also ameliorated dyslipidemia in T2DM patients." (PMID 38707340, 2024). "Finally, DPP4 expression levels positively correlated with adipocyte size and with the presence of metabolic syndrome." (PMID 36140405, 2022). "In obese T2DM and metabolic syndrome patients, increased expression and membrane shedding of DPP4 suggest that this novel adipokine could be a marker for visceral obesity, metabolic syndrome, and IR." (PMID 35885620, 2022). "However, DPP4 activity correlates with various parameters which are altered within the course of metabolic syndrome." (PMID 33192409, 2020). "Considering the 12-month period from baseline, the HRs of the DPP-4 inhibitors and dyslipidemia were significantly lower at eGFR decline rates of >10, >20, and >30%, indicating that DPP-4 inhibitors and dyslipidemia suppressed the eGFR decline at all thresholds examined in this study." (PMID 29187821, 2017). "Similarly, DPP-4 inhibitors (HR, 0.707; 95% CI, 0.572–0.874; P = 0.001), dyslipidemia (HR, 0.710; 95% CI, 0.551–0.915; P = 0.008), and ACEI/ARBs (HR, 0.622; 95% CI, 0.446–0.868; P = 0.005) reduced the risk of eGFR decline >30%." (PMID 29187821, 2017). "In addition, DPP4 release by adipose tissue was correlated with adipocyte size and features of the metabolic syndrome." (PMID 25816202, 2015). "Since soluble DPP4 is characterized as an adipokine and also correlates with parameters of the metabolic syndrome, it might also be an important molecular biomarker." (PMID 26284071, 2015). "ORs for new-onset metabolic syndrome in women according to baseline DPP4 activity and active GLP-1." (PMID 24647445, 2014). "ORs for new-onset metabolic syndrome in men according to baseline DPP4 activity and active GLP-1." (PMID 24647445, 2014). "In our study, we found that plasma DPP4 activity was significantly higher in subjects who had higher WHR, blood pressure, blood lipid and HOMA-IR, furthermore, we also found that increased DPP4 activity is an independent predictor of metabolic syndrome and its components in our prospective study." (PMID 24647445, 2014). "Furthermore, plasma DPP4 activity progressively increased with the number of metabolic syndrome components developed by study participants over follow-up whereas active GLP-1 decreased progressively (P for trend <0.001 in both men and women)." (PMID 24647445, 2014). "Furthermore, plasma DPP4 activity significantly improved the area under the ROC curve for predicting new-onset metabolic syndrome based on information from metabolic syndrome components (Both P<0.01)." (PMID 24647445, 2014). "Research suggests that GLP-1 may have beneficial effects on dyslipidemia, and recent small studies with DPP-4 inhibitors have shown favorable effects or a neutral effect on postprandial dyslipidemia in patients with T2DM." (PMID 23570327, 2013).
metabolic syndrome (continued). "However, recent studies suggest the potential of newly identified drugs including thiazolidinediones, GLP-1 agonists, and DPP-4 inhibitors that seem to be promising in reducing the level of progression of metabolic syndrome related disorders." (PMID 22615610, 2010). "DPP4i: dipeptidyl peptidase 4 inhibitor; HbA1C: glycated haemoglobin; MetS index: metabolic syndrome index; SGLT2i: sodium-glucose cotransporter-2 inhibitor; SU: sulfonylurea." (PMID 39252700, 2024). "In addition to hepatosteatosis, the first data were very recently published on DPP4 levels in human epicardial adipose tissue (EAT), which is known to accumulate in dysmetabolic conditions and is a marker of metabolic syndrome and increased cardiovascular risk." (PMID 36140405, 2022). "In this study, nitrate and nitrite levels and the effects of DPP-4 inhibitor linagliptin were investigated in relation to metabolic syndrome (MetS) markers." (PMID 34679685, 2021). "DPP-4 inhibitors had been expected to confer beneficial effects on CV disease (CVD) due to pleiotropic effects as they show positive effects on CV risk factors in T2DM patients, such as weight loss, reduced blood pressure, improved postprandial dyslipidemia, and reduced inflammation." (PMID 33149182, 2020). "Therefore, in this study we analyzed the gender differences between plasma GLP-1 and DPP4 activity in patients with metabolic syndrome and in their corresponding age-matched controls, as well as their relationship with some physiological and metabolic parameters." (PMID 29958403, 2018). "Therefore, it has been suggested that DPP-4 may be involved in linking adipose tissue and the metabolic syndrome." (PMID 27652270, 2016). "Dipeptidyl peptidase 4 (DPP- 4), also known as CD26 is one of the main molecules involved in the pathology of metabolic syndrome such as T2DM." (PMID 34094026, 2021). "Future studies will be required to evaluate the effects of DPP-4 inhibition and knockout approaches on platelet reactivity in DM2 and metabolic syndrome." (PMID 33328991, 2020). "On the other hand, pioglitazone’s effect in lipid lowering via regulation of adipogenesis remained intact in ESRD patients, which could be supported by our observation that patients with underlying dyslipidemia benefit more from pioglitazone rather than DPP4-inhibitors." (PMID 33172034, 2020). "We then evaluated how well baseline DPP4 activity and active GLP-1 levels predict incident metabolic syndrome beyond the information provided by baseline levels of metabolic syndrome components." (PMID 24647445, 2014). "Nonetheless, the most remarkable outcome of the analysis is that DPP4 expression before HSCT (as well as its Δmean and Δmean(rel)) could be used to anticipate the presence of dyslipidemia in children after transplantation." (PMID 34298827, 2021). "Significantly greater changes in DPP4 expression were found in children who presented any laboratory features of dyslipidemia after HSCT compared to those who did not (Δmean: 328.2 ± 204.0 vs. 46.0 ± 166.6, p/pBH = 0.002/0.006)." (PMID 34298827, 2021). "Two years later, the same group analyzed DPP4 gene methylation levels between obese subjects with and without the metabolic syndrome in visceral adipose tissue." (PMID 26284071, 2015). "However, the complete absence of DPP4 (Dpp4–/–) in aged mice with metabolic syndrome accelerates liver fibrosis without altering dyslipidemia and steatosis." (PMID 36472923, 2023). "Firstly, the follow-up period of our cohort was only 4 years, and we could not evaluate whether the association between DPP4 activity, active GLP-1 and incident metabolic syndrome would persist in longer follow up." (PMID 24647445, 2014). "Patients were not taking other drugs for treating dyslipidemia nor any anti-diabetic drugs that could affect the lipid profile such as thiazolidinediones, glucagon-like peptide-1 agonists, dipeptidyl peptidase 4 inhibitors or sodium-glucose co-transporter-2 inhibitors." (PMID 31409878, 2019).
metabolic syndrome (continued). "Baseline DPP4 activity and active GLP-1 according to presence or absence of components of new-onset metabolic syndrome." (PMID 24647445, 2014). "However, among children with dyslipidemia features after HSCT, the reduction in DPP4 expression was high, while in patients with no lipid metabolism abnormalities, the change was small." (PMID 34298827, 2021).
diabetic nephropathy (74 papers, 2013 to 2025). "It is important to note that diabetic nephropathy is associated with an upregulation of DPP-4 expression, suggesting the role of DPP-4 as a potential therapeutic target for the management of this condition." (PMID 40843763, 2025). "Our study also found that SGLT2 inhibitors reduced the risk of hospitalisations (except for CVD hospitalisations and hospitalisations for diabetic nephropathy) and all-cause death compared to DPP4 inhibitors." (PMID 35673518, 2022). "The results of the present study promise to advance our understanding of how ACEi regulates antifibrotic microRNAs crosstalk and DPP-4 associated-fibrogenic processes which is a critical event in the development of diabetic kidney disease." (PMID 32085655, 2020). "Dipeptidyl peptidase 4 inhibitor (DPP4i) use potentially slows the progression of diabetic kidney disease, but its effects on the risk of acute kidney injury (AKI) are unclear." (PMID 28881791, 2017). "In animal experiments, DPP4 deficiency or the addition of a DPP4 inhibitor could protect against experimental diabetic nephropathy in a glucose-lowering- independent manner." (PMID 33261212, 2020). "If this is also borne out in clinical trials, DPP4 inhibition with linagliptin may have an added advantage in those at risk of diabetic nephropathy." (PMID 26509887, 2015). "For example, in an experimental study in 2016 in mice, using Linagliptin, a DPP-4 inhibitor, was associated with upregulation of stromal cell-derived Factor-1, which contributes as an antioxidative and anti-fibrotic agent in the pathophysiology of diabetic nephropathy." (PMID 35610696, 2022). "DPP-4 inhibitors, especially when combined with insulin or metformin, also improve endothelial dysfunction in diabetic kidney disease (DKD)." (PMID 40303495, 2025). "Some studies have shown that DPP4 inhibitors can alleviate kidney diseases, such as diabetic nephropathy, hypertensive nephropathy, and crescentic nephritis." (PMID 38762508, 2024). "DPP-4 is expressed in human kidneys and up-regulated in the glomeruli of patients with diabetic nephropathy." (PMID 37532063, 2023). "Increased GLP-1 in DPP-4 deficient mice has been shown to regulate AGE formation and improve diabetic nephropathy." (PMID 38258046, 2023). "In various studies, DPP-4 inhibitors have been shown to exert nephroprotective effects independent of their blood sugar-controlling effects and have curative effects on diabetic nephropathy." (PMID 35530894, 2022). "The role of DPP4 and its inhibitors is now also being studied to target fibrotic and inflammatory pathways in diabetic nephropathy conditions, making it an upcoming target." (PMID 35956932, 2022). "We evaluated the effects of a potent DPP4 inhibitor (gemigliptin) on these processes among patients with diabetic kidney disease (DKD)." (PMID 34697593, 2021). "This trial originally demonstrated the efficacy in terms of glycemic control of linagliptin, a dipeptidyl peptidase-4 inhibitor, when added to standard treatment in patients with diabetic kidney disease." (PMID 35008760, 2021). "The data provide a new explanation for the mechanism of the renoprotective action of SGLT2 inhibitors and DPP4 inhibitors in diabetic kidney disease." (PMID 32340263, 2020). "DPP-4 activity was observed in crescent formation in anti-neutrophil myeloperoxidase cytoplasmic antigen antibody nephritis, nodular lesions in diabetic nephropathy, and some podocytes in focal segmental glomerulosclerosis." (PMID 32948146, 2020). "The role of DPP-4 and the effects of DPP-4 inhibitors in diabetic kidney disease have been reviewed recently, with a focus on linagliptin (see." (PMID 33519447, 2020). "The effect of DPP-4 inhibitors on diabetic nephropathy was evaluated in many studies, but few clinical trials about this topic have been conducted so far." (PMID 32190049, 2020). "miR-29 directly targets DPP-4; therefore, DPP-4 inhibition is proposed for the therapy of diabetic nephropathy." (PMID 31474862, 2019).